ITSN1 (intersectin 1)
Diseases named in the same sentence as ITSN1 in open-access papers (continued):
Sharing a sentence is not in itself a finding about the gene and the disease.
inflammatory bowel disease (5 papers, 2020 to 2025). A spectrum of small and large bowel inflammatory diseases of unknown etiology. "Our findings indicates that the ITSN1-2/ceRNA axis may serve as a therapeutic target in NOD2/RIP2-driven diseases (e.g., cancer, RA, inflammatory bowel disease), but its inverse regulation in other disease like in SLE underscores the need for disease-specific biomarker panels." (PMID 40629453, 2025). "Moreover, lnc-ITSN1-2 may promote the differentiation of T helper type 1 (Th1) and Th17 cells in CD4+ T cells of inflammatory bowel disease (IBD) via regulating the microRNA (miR)-125a/interleukin (IL)-23R axis." (PMID 34406596, 2021).
rheumatoid arthritis (5 papers, 2020 to 2025). A chronic, systemic autoimmune disorder characterized by inflammation in the synovial membranes and articular surfaces. "Downregulation of lncRNA ITSN1-2 is associated with rheumatoid arthritis (RA)." (PMID 37600601, 2021). "Synovial tissues were collected from 24 rheumatoid arthritis (RA) patients and 20 osteoarthritis (OA) patients to observe the lncRNA ITSN1-2/NOD2/RIP2 signal in RA synovial tissue and its correlation with RA inflammation and bone destruction." (PMID 40629453, 2025). "As a newly identified lncRNA, lncRNA intersectin 1-2 (lnc-ITSN1-2) may induce inflammation in the fibroblast-like synoviocytes (FLS) of rheumatoid arthritis (RA) through promoting the nucleotide-binding oligomerization domain 2 (NOD2)/receptor-interacting protein 2 (RIP2) axis." (PMID 34406596, 2021). "Long non-coding RNA ITSN1-2(lncRNA ITSN1-2) promotes fibroblast-like synovicytes (FLS) proliferation and suppress apoptosis through activation of the NOD2/RIP2 signaling pathway, thereby exacerbating synovitis in Rheumatoid arthritis (RA) pathology." (PMID 40629453, 2025).
Cognitive impairment (3 papers, 2020 to 2022). Abnormal cognition is characterized by deficits in thinking, reasoning, or remembering. "Autistic individuals with LoF variants in the four moderate-risk genes (NAV3, ITSN1, SCAF1 and HNRNPUL2; n = 95) have less cognitive impairment than 129 autistic individuals with LoF variants in highly penetrant genes (CHD8, SCN2A, ADNP, FOXP1 and SHANK3) (59% vs 88%, P = 1.9 × 10−6)." (PMID 35982159, 2022). "Consistent with the cognitive deficits observed, LTP was decreased in ITSN1-LKO mice compared with the WT for both 9–12 weeks and 6 months age groups." (PMID 32161523, 2020).
schizophrenia (3 papers, 2012 to 2024). A major psychotic disorder characterized by abnormalities in the perception or expression of reality. "ITSN1 has been implicated in neurodegeneration and the identification of ITSN1 as a binding partner for DISC1 (disrupted in schizophrenia 1) suggests a potential role for ITSN1 in psychiatric disease as well." (PMID 22558309, 2012). "Notably, ITIH3, ITIH4, and NT5C2 were selected for depression, while PSMA4 and ITSN1 were identified for schizophrenia." (PMID 38637810, 2024). "Furthermore, ITSN1 was identified as a binding partner for DISC1 (disrupted in schizophrenia 1) suggesting a potential role in psychiatric disease as well." (PMID 22558309, 2012).
breast carcinoma (2 papers, 2020 to 2021). "Then we performed immunohistochemistry (IHC) to examine the localization of ITSN1-S, the major isoform of ITSN1 in breast cancer in breast cancer tissues." (PMID 34625530, 2021). "Volcano plots showed that the mRNA level of ITSN1 was lower in breast cancer tissues compared with adjacent normal tissues." (PMID 34625530, 2021). "Next, survival analysis of the Kaplan–Meier-plotter database showed that breast cancer patients with higher ITSN1 mRNA expression had a better overall survival (OS) and relapse-free survival (RFS) compared with those with lower ITSN1 mRNA expression." (PMID 34625530, 2021). "The data from the GEPIA database showed that ITSN1 mRNA level in breast cancer tissues was lower than normal tissues." (PMID 34625530, 2021). "It suggested an important role of ITSN1 in the suppression of breast cancer progression." (PMID 34625530, 2021). "The ITSN1 gene is being considered a key biological target candidate for breast cancer." (PMID 32784507, 2020).
Crohn disease (2 papers, 2020 to 2021). A gastrointestinal disorder characterized by chronic inflammation involving all layers of the intestinal wall, noncaseating granulomas affecting the intestinal wall and regional lymph nodes, and transmural fibrosis. "lnc-ITSN1-2 expression also correlates with disease risk and active disease status of IBD, and it positively correlates with CRP, ESR, and Crohn’s disease activity index in patients with active Crohn’s disease (CD)." (PMID 34406596, 2021). "Intestinal mucosa and PBMC lnc-ITSN1-2, IL-23R, and inflammatory cytokines were measured in 120 IBD patients [60 Crohn's disease (CD) and 60 ulcerative colitis (UC)] and 30 HCs." (PMID 32547537, 2020).
dementia (2 papers, 2019 to 2024). Loss of intellectual abilities interfering with an individual's social and occupational functions. "Phosphorylation levels in these networks were inversely related to learning and linked to synaptic dysfunction, cognitive decline, and dementia including Atp6v1a and Itsn1." (PMID 38542311, 2024). "Although this study reported that ITSN1 is overexpressed in the AD brain, there is nothing in the literature about the expression of ITSN1 at the protein level or in other types of dementia." (PMID 31263630, 2019). "Similarly, it is not possible to predict in what way our data for levels of ITSN1 protein in dementia brains would have been affected." (PMID 31263630, 2019).
Huntington disease (2 papers, 2012 to 2013). Huntington disease (HD) is a rare neurodegenerative disorder of the central nervous system characterized by unwanted choreatic movements, behavioral and psychiatric disturbances and dementia. "ITSN1 has been implicated in neurodegeneration through its link with regulation of the JNK MAPK pathway and its association with several proteins that interact with the protein product of the Huntington's Disease gene." (PMID 22558309, 2012).
Intellectual disability (2 papers, 2019 to 2022). "Interestingly, of the six ASD cases with LGD variants in ITSN1, five do not have intellectual disability." (PMID 31452935, 2019). "For both ITSN1 and NAV3, we identified four partial or whole gene deletions in 33,083 parents without ASD diagnoses or intellectual disability that also show transmission disequilibrium to affected offspring." (PMID 35982159, 2022).
memory impairment (2 papers, 2020 to 2024). "Overall, this study demonstrated that EE is effectively reversed the SI induced memory impairment by potentially regulating the molecules associated with the ITSN1-Reelin–AMPA receptor pathway to increase synaptic plasticity." (PMID 38241230, 2024).
prostate carcinoma (2 papers, 2020). A carcinoma that arises from epithelial cells of the prostate gland. "The importance of ITSN1 deletion in prostate cancer still awaits future studies." (PMID 32784507, 2020). "The reference-free diagnostic panel used the ratio of relative expression of three mRNAs that are overexpressed (FOLH1, XBP1 and HPN) to five mRNAs that are underexpressed (ITSN1, GSTM4, LTBP4, NELL2, and CFD) in prostate cancer compared to normal tissue." (PMID 33172003, 2020).
pulmonary arterial hypertension (2 papers, 2017 to 2018). Pulmonary arterial hypertension (PAH) is a group of diseases characterized by mean pulmonary artery pressure >20 mmHg and elevated pulmonary arterial resistance leading to right heart failure. "Intersectin-1s (ITSN) deficiency and expression of a biologically active ITSN fragment, result of granzyme B cleavage under inflammatory conditions associated with pulmonary arterial hypertension (PAH), are characteristics of lung tissue of human and animal models of PAH." (PMID 30333761, 2018).
Stroke (2 papers, 2020 to 2021). Sudden impairment of blood flow to a part of the brain due to occlusion or rupture of an artery to the brain. "In order to investigate the correlation of lnc‐ITSN1‐2 expression with AIS patients’ prognosis, we further recorded stroke recurrence and death with follow‐ups of 36 months, and we discovered that increased lnc‐ITSN1‐2 expression was associated with worse RFS in AIS patients." (PMID 31647141, 2020). "One study showed that lnc-ITSN1-2 expression was positively correlated with the National Institutes of Health Stroke Scale (NIHSS) score and reflected the severity of stroke." (PMID 34867389, 2021).
Adult onset (1 paper, 2025). Onset of disease manifestations in adulthood, defined here as at the age of 16 years or later. "The spectrum of phenotypes associated with ITSN1 haploinsufficiency, ranging from apparently unaffected carriers to individuals with increased risk of childhood-onset ASD or adult-onset neurodegenerative diseases, suggests variable penetrance and/or expressivity of ITSN1 mutations." (PMID 40056900, 2025).
amyloid (1 paper, 2024). "To examine if the changes in ITSN1 we observed in human AD brains also occur in an AD mouse model with amyloid pathology, we performed immunoblots on the CTX and HP of 5xFAD and WT littermate controls." (PMID 38915309, 2024).
autism spectrum disorder (1 paper, 2025). A spectrum of developmental disorders that includes autism, and Asperger syndrome. "It is notable, however, that haploinsufficiency of ITSN1 has recently been associated with autism spectrum disorder (ASD) and episodic memory decline." (PMID 40056900, 2025). "Notably, ITSN1 haploinsufficiency has also been associated with autism spectrum disorder, suggesting variable penetrance/expressivity." (PMID 40056900, 2025).
autosomal dominant non-syndromic intellectual disability (1 paper, 2023). Autosomal dominant form of non-syndromic intellectual disability. "Diseases associated with ITSN1 include autosomal dominant non-syndromic intellectual disability and esophageal atresia." (PMID 37019990, 2023).
cervical cancer (1 paper, 2021). A primary or metastatic malignant neoplasm involving the cervix. "WDR19 and ITSN1 are also likely susceptibility genes of cervical cancer." (PMID 33403041, 2021). "Particularly, with regards to the four non-MHC genes, we observe that, besides WDR19, ITSN1 is also detected to be marginally related to cervical cancer (p = 0.081) in the EAS population." (PMID 33403041, 2021).
coronary artery disease (1 paper, 2020). "Additionally, lnc-ITSN1-2 is reported to be implicated in the pathology of RA and may serve as a potential biomarker for coronary artery disease risk, thus we hypothesized that lnc-ITSN1-2 might be involved in IBD pathogenesis as well." (PMID 32547537, 2020). "Since lnc-ITSN1-2 was one of the most dysregulated DELs in IBD patients, as indicated by our RNA sequencing data, and it was reported to be implicated in the pathology of RA and might serve as a potential biomarker for coronary artery disease risk." (PMID 32547537, 2020).
cystic kidney disease (1 paper, 2025). A congenital or acquired kidney disorder characterized by the presence of renal cysts. "Seven genes (3%) had no entries in OMIM (DLG5 in renal ciliopathies and cystic kidney diseases; and 6 in the proteinuric kidney diseases [APOE, DLC1, FAT1, ITSN1, PODXL and TNS2]) and were excluded." (PMID 40303230, 2025).
Iron deficiency (1 paper, 2019). "Iron deficiency altered methylation at the genes regulating ephrin B signaling/ephrin receptor signaling (data not shown), including increased methylation at Ephb1, Itsn1, Prkar1b, and Srgap2, and decreased methylation at Arhgef15, Mknk1, and Slit3 loci." (PMID 31137889, 2019).
malignant glioma (1 paper, 2022). A grade III or grade IV glioma arising from the central nervous system. "Therefore, PTBP1, as the key splicing regulator of ITSN1, should be treated as a promising therapeutic target for suppressing the progress of malignant gliomas." (PMID 36171198, 2022).
nephrosis (1 paper, 2018). Pathological processes of the KIDNEY without inflammatory or neoplastic components. "To test whether loss of function of ITSN1 and ITSN2 GEF activity causes a nephrosis phenotype in humans, we examined the effect of mutations identified in patients with pTSNS on the active states of Cdc42." (PMID 29773874, 2018).
nephrotic syndrome (1 paper, 2020). A collection of symptoms that include severe edema, proteinuria, and hypoalbuminemia; it is indicative of renal dysfunction. "Mutations in FAT1, intersectin 1 (ITSN1), and ITSN2 genes have all been reported to cause nephrotic syndrome due to their adverse effects on Cdc42 activation resulting in impaired podocyte migration." (PMID 32708597, 2020).
Neurofibrillary tangles (1 paper, 2025). Pathological protein aggregates formed by hyperphosphorylation of a microtubule-associated protein known as tau, causing it to aggregate in an insoluble form. "One of the enhanced proteins, ITSN1, is a key component of the Reelin signaling pathway and thus may have the potential to act in conjunction with sCLU to reduce levels of p-tau and thus neurofibrillary tangle formation." (PMID 40322539, 2025).
pancreatic cancers (1 paper, 2013). "ITSN1 is overexpressed in pancreatic cancers suggesting that upregulation of the ITSN1-PI3KC2β signaling pathway may contribute to development of pancreatic cancers as well." (PMID 23574942, 2013).
systemic lupus erythematosus (1 paper, 2025). An autoimmune multi-organ disease typically associated with vasculopathy and autoantibody production. "In contrast, in PBMCs, lower expression of lncRNA ITSN1-2 compared to healthy individuals and systemic lupus erythematosus (SLE) patients, with a negative correlation to CRP levels." (PMID 40629453, 2025).
tumor (11 papers, 2013 to 2026). "Among all 32 putative target genes of miR-193a-5p, we identified four tumor-associated genes, including CUX1, ITSN1, OLA1, and RAP2A." (PMID 33014778, 2020). "LN229/HA-DH-PH-C2 mice group showed similar tumor volume compared to control, while ITSN1 knockout group showed the smallest tumor volume." (PMID 31160551, 2019). "Among them, we revealed that miR-193a-5p could inhibit CRC migration and invasion via targeting tumor-associated genes like CUT-like homeobox 1 (CUX1) and intersectin 1 (ITSN1)." (PMID 33014778, 2020). "Met, Itsn1, and Acot1 all show a pivotal role in tumor development; however, the role of these genes in MDSCs is currently unknown." (PMID 32290071, 2020).
cancer (8 papers, 2013 to 2025). A tumor composed of atypical neoplastic, often pleomorphic cells that invade other tissues. "In the case of NBs, overexpression of the ITSN1 target PI3KC2β rescued the anchorage-independent growth of ITSN1- silenced cells suggesting a role for this ITSN1 effector in human cancers." (PMID 23574942, 2013). "Several recent studies provide direct evidence for ITSN1 involvement in human cancers." (PMID 23574942, 2013).
inflammation (2 papers, 2020 to 2025). Aberrant reaction of the microcirculation characterized by movement of fluid and leukocytes from the blood into extravascular tissues. "Similarly, few studies have been performed to investigate the role of lnc‐ITSN1‐2 in inflammation‐related diseases." (PMID 31647141, 2020). "Our prior work demonstrated that lncRNA ITSN1-2 enhances NOD2/RIP2 signaling, promoting FLS proliferation and inhibiting apoptosis, thereby exacerbating synovial inflammation in RA." (PMID 40629453, 2025).
neurodegenerative disease (2 papers, 2020 to 2025). A disorder of the central nervous system characterized by gradual and progressive loss of neural tissue and neurologic function. "Family history of neurodegenerative disease is frequent in ITSN1 PTV carriers with PD, suggesting that some of these variants may be inherited rather than de novo." (PMID 40056900, 2025).
ITSN1 also shares sentences with these, for which no sentence is quoted: Parkinson disease (3 papers); ankylosing spondylitis (2); developmental delay (2); infection (2); lung carcinoma (2); acute lung injury (1); acute pancreatitis (1); arteriopathy (1); cognitive decline (1); colorectal cancer (1); Dementia with Lewy bodies (1); depression (1); diabetes mellitus (1); digestive system neoplasm (1); Esophageal atresia (1); glioblastoma (1); hyperlipidemia (1); Hypertension (1); hyperuricemia (1); ischemia (1); leukaemia (1); liver cancer (1); microcephaly (1); neurological diseases (1); osteoarthritis (1); pancreatic ductal adenocarcinoma (1); Parkinsonism (1); psychiatric disease (1); spondylitis (1); ulcerative colitis (1).
A further 1 disease shares a sentence with ITSN1 in 1 paper.